CARD14 (caspase recruitment domain family member 14)
Diseases named in the same sentence as CARD14 in open-access papers (continued):
Sharing a sentence is not in itself a finding about the gene and the disease.
cancer (4 papers, 2005 to 2024). A tumor composed of atypical neoplastic, often pleomorphic cells that invade other tissues. "In this context, our observation that high CARD14 expression in PCa patients correlates with more aggressive PCa, together with the finding that CARD14 expression is essential for survival of LNCaP PCa cells, reveal CARD14 as a novel anti-cancer target in PCa." (PMID 36009554, 2022). "By analysing existing cancer databases, we found that CARD14 overexpression strongly correlates with aggressive PCa in human patients." (PMID 36009554, 2022). "In agreement with this, TCGA analysis revealed that CARD14 levels also correlate with cancer recurrence in PCa patients." (PMID 36009554, 2022). "CARD14 isoforms are expressed in several hematopoietic cells and tissues such as bronchus, cervix, colon and lung as well as cancer cell lines derived from these tissues." (PMID 34012923, 2021). "CARD14 expression appeared to be greater in primary cancer and reduced in bone metastasis while that of ACAS2L and PLD1 appeared to be equivalent." (PMID 16042785, 2005). "Caspase recruitment domain family member 14 (CARD14), expression appeared to be elevated in primary cancer but reduced in lymph node and bone metastasis." (PMID 16042785, 2005). "The signalling adapter protein CARD14 is specifically expressed in epithelial cells, where it has been shown to mediate NF-κB signalling, but a role for CARD14 in carcinoma has not yet been described." (PMID 36009554, 2022).
tumor (2 papers, 2022 to 2023). "Overexpression of CARD14 was also significantly associated with lymph node metastasis, while CARD14 expression was found to be higher in metastatic PCa tumours compared with primary PCa tumours." (PMID 36009554, 2022). "Finally, high CARD14 expression was also found to correlate with higher proliferation in tumour tissue." (PMID 36009554, 2022). "In addition, expression of CARD14 is higher in tumour tissue as opposed to (paired) healthy tissue." (PMID 36009554, 2022).
inflammation (1 paper, 2025). Aberrant reaction of the microcirculation characterized by movement of fluid and leukocytes from the blood into extravascular tissues. "CARD14(E138A)IEC mice are also a valuable tool for further investigation of IEC-intrinsic molecular processes involved in intestinal inflammation and motility disorders." (PMID 41131424, 2025).
respiratory diseases (1 paper, 2023). "For example, genes associated with respiratory diseases and cell proliferation (CA5B, ID2, CARD14 and TRIM29) were significantly altered." (PMID 36673815, 2023).
CARD14 also shares sentences with these, for which no sentence is quoted: psoriatic arthritis (6 papers); dermatitis (3); acne (2); impetigo herpetiformis (2); localized pustular psoriasis (2); Majeed syndrome (2); metabolic syndrome (2); pyoderma gangrenosum (2); atherosclerosis (1); autoimmune disease (1); autoimmune thyroid disease (1); autosomal recessive congenital ichthyosis (1); Blau syndrome (1); cardiovascular disease (1); dyskeratosis congenita (1); familial cold autoinflammatory syndrome 4 (1); familial hyperlipidemia (1); familial Mediterranean fever (1); ichthyosis vulgaris (1); inflammatory bowel disease (1); keratosis (1); Legionnaires' disease (1); Mendelian diseases (1); Obesity (1); Palmoplantar keratoderma (1); pityriasis rosea (1); porokeratosis (1); pyogenic arthritis (1); sarcoidosis (1); skin changes (1).
A further 2 diseases each share a sentence with CARD14 in 1 paper.